CLEC4F (C-type lectin domain family 4 member F)
Description:
Receptor with an affinity for galactose and fucose. Could be involved in endocytosis (By similarity).
Synonyms: CLECSF13; FLJ39110; KCLR; KCR
Tractability: Antibody: UniProt predicts a signal peptide or a membrane-spanning region; the Human Protein Atlas places it where antibodies can reach.
Gene: Protein-coding gene on chromosome 2 (70,808,643 to 70,820,599, reverse strand). Ensembl gene ENSG00000152672.
Subcellular location: Membrane
Subcellular location (Human Protein Atlas): Plasma membrane; Cytosol
Gene Ontology:
Molecular function: carbohydrate binding; pattern recognition receptor activity
Biological process: immune response
Cellular component: external side of plasma membrane; membrane
Genetic constraint (gnomAD): Loss-of-function variants: 42 observed, 52.44 expected, observed/expected ratio (o/e) 0.8, 90% interval 0.62 to 1.04. The upper end of that interval is the gene's LOEUF score, 1.04, which puts it in group 4 of 6, group 1 being the genes least tolerant of losing a copy. Missense variants: 746 observed, 716.62 expected, observed/expected ratio (o/e) 1.04, 90% interval 0.98 to 1.11. Synonymous variants: 245 observed, 266.33 expected, observed/expected ratio (o/e) 0.92, 90% interval 0.83 to 1.02.
Homologues: Orthologues: chimpanzee CLEC4F (97% identical), macaque CLEC4F (84% identical), pig CLEC4F (60% identical), dog CLEC4F (59% identical), guinea pig CLEC4F (54% identical), mouse Clec4f (46% identical), rat Clec4f (46% identical), zebrafish zgc:174904 (10% identical), zebrafish si:ch211-133n4.7 (9% identical), zebrafish illr2 (8% identical), zebrafish illr1 (8% identical), zebrafish illr3 (8% identical), and 13 more. Paralogues in human: CD207 (18% identical), ASGR2 (11% identical), FCER2 (10% identical), ASGR1 (10% identical), CLEC10A (10% identical), CLEC17A (9% identical), CLEC4G (9% identical), CD209 (9% identical), CLEC4M (9% identical), CLEC6A (8% identical), CLEC4D (7% identical), CLEC4E (7% identical), and 2 more.
Diseases named in the same sentence as CLEC4F in open-access papers:
CLEC4F is named in the same sentence as 12 diseases in open-access papers, as found by Europe PMC text mining. Sharing a sentence is not in itself a finding about the gene and the disease. The quoted sentences say what the papers report.
Sepsis (2 papers, 2021 to 2025). Sepsis is defined as life-threatening organ dysfunction caused by a dysregulated host response to infection. "Future studies in these pathological conditions will provide new insights into the role of Kupffer cell receptor CLEC4F in disorders with thrombocytopenia such as sepsis and ITP." (PMID 33993195, 2021). "Collectively, these findings identify CLEC4F as a Kupffer cell receptor important for the destruction of desialylated platelets induced by bacteria-derived neuraminidases, which provide new insights into the pathogenesis of thrombocytopenia in disease conditions such as sepsis." (PMID 33993195, 2021). "In addition, IL-1R2 expression is minimal in cluster 9, which co-expressed Adgre1, Clec4f and Tim4 and identified as resident macrophages, namely Kupffer cells in the liver, and this expression did not increase in response to sepsis." (PMID 41293423, 2025).
Acute hepatitis (1 paper, 2020). Acute hepatic injury resulting from inflammation typically accompanied by increased serum alanine transaminase activity. "In addition to Vsig4, Nbs targeting C-type lectin domain family 4 member F (Clec4F) have been used to monitor KC dynamic during liver inflammation by SPECT: 99mTC-labeled anti-Clec4F Nb accumulation is reduced in a ConA-induced acute hepatitis model." (PMID 33353213, 2020).
Granuloma (1 paper, 2025). A compact, organized collection of mature mononuclear phagocytes, which may be but is not necessarily accompanied by accessory features such as necrosis. "In contrast, late-stage granulomas led to remodeling of the sinusoidal network and contained monocyte-derived macrophages (momacs) along with KCs that downregulated CLEC4F, with both populations expressing iNOS and pro-inflammatory chemokines." (PMID 40169598, 2025). "Consistently, most CLEC4F-KCs and momacs were observed within granulomas, while resKCs and moKCs were predominantly outside granulomas." (PMID 40169598, 2025). "Our findings support this idea, demonstrating that some F4/80+ cells inside the sinusoids were CLEC4F+moKCs, and suggesting that KC redistribution during granuloma formation triggers repopulation of the sinusoidal niche by moKCs." (PMID 40169598, 2025). "Consistent with whole-liver observations, analysis of the cellularity within the granulomas revealed that CLEC4F+TIM-4+resKCs were the principal subset found within early-stage granulomas at 19 d.p.i." (PMID 40169598, 2025). "As granulomas expand and other cells, such as momacs, surround the KC core, the sinusoidal network is displaced, leading to resKCs losing their contact with the sinusoids and downregulating their CLEC4F expression." (PMID 40169598, 2025). "Early-stage granulomas predominantly consisted of CLEC4F+KCs." (PMID 40169598, 2025). "In late-stage granulomas, KCs at the core downregulated CLEC4F and expressed iNOS and pro-inflammatory chemokines, but otherwise maintained a gene expression profile largely similar to that of CLEC4F+resKCs." (PMID 40169598, 2025). "However, by 42 d.p.i., these cells were significantly reduced in granulomas, which were predominantly populated by CLEC4F-TIM-4+ and CLEC4F-TIM-4− cells." (PMID 40169598, 2025).
Hepatic steatosis (1 paper, 2025). Steatosis is a term used to denote lipid accumulation within hepatocytes. "Histological analysis of these mice revealed markedly aggravated hepatic steatosis, an increased CLEC4F-positive KC population and liver ballooning." (PMID 39939782, 2025).
Listeria monocytogenes infection (1 paper, 2021). "The determined molecular structure presented here will help in developing blocking nanobodies, which may find applications in blocking Clec4F interactions in disease models such as Listeria monocytogenes infection." (PMID 33692811, 2021). "Moreover, Clec4F was reported to be involved in the Listeria monocytogenes infection in mouse liver." (PMID 33692811, 2021).
liver failure (1 paper, 2025). A liver disease characterized by the liver losing or has lost all of its function. "Loss of mature CLEC4F-positive KCs leads to a liver failure-like phenotype in alcohol-fed mice." (PMID 40824250, 2025).
tumor (10 papers, 2007 to 2026). "Based on this finding, we used Clec4f as a KC-specific marker to study interactions between tumor cells and liver macrophage subsets using multiplex immunohistochemistry (mIHC)." (PMID 37816712, 2023). "Seeding tumor cells were more frequently detected in contact with a F4/80+ BMDM than F4/80+Clec4f+ KC." (PMID 37816712, 2023). "First, we observed that the number of KC (CD45+ CD11bint F4/80+ Tim4+ Clec4F+ Ly6G− cells) progressively increased and reached maximal value 9 days after tumor inoculation in the H group of mice compared with the sham group of mice (placebo treatment)." (PMID 33178579, 2020). "TIM4+CLEC4F+ KCs were always located outside and around the liver tumour nodules in an endogenous tumour model with spontaneous metastases (KPC mice), as well as in the orthotopic graft model, and in short-term models after intraportal injection of five different carcinoma and melanoma cell lines." (PMID 38326607, 2024). "Immunostaining further confirmed that tumor-associated macrophages (TAMs) were non-KC macrophages (F4/80+ and Clec4f-), a population expanded in Shp2DK mice." (PMID 36828281, 2023). "In addition, CLEC4F+ Kupffer cells are known to promote angiogenesis and tumor invasion." (PMID 39875968, 2025). "To validate this observation, we employed flow cytometry to assess FABP7 expression in CLEC4F+ F4/80+ KCs and CX3CR1+ F4/80+ MoMFs from the liver PMN and MMN of MC38 tumor-bearing mice." (PMID 40765822, 2025). "Tumor‐associated macrophages (F4/80+TIM4−) are clustered within the tumor nodules, while KCs (TIM4+CLEC4F+) form a peritumoral niche consistently surrounding the tumor nodules." (PMID 39220104, 2024).
infection (5 papers, 2013 to 2025). The state of being infected such as from the introduction of a foreign agent such as serum, vaccine, antigenic substance or organism. "The liver-specific expression of Clec4F in rodents would also match the fact that the liver is the primary infection site of larval E. multilocularis in its rodent hosts." (PMID 36929004, 2023). "We found that both the numbers of CLEC4F+ and F4/80+ cells were increased dramatically at day 1 post-infection, and increased at day 5 post-infection in wild-type mice." (PMID 23762286, 2013). "mice (“early-stage infection”), the majority of F4/80+ macrophages were CLEC4F+TIM-4+resKCs." (PMID 40169598, 2025). "In the natural hosts of larval E. granulosus, the situation is more complex: non-liver (particularly lung) infections are common, and Clec4F is probably expressed extra-hepatically in addition to in the liver." (PMID 36929004, 2023). "In the absence of recruited macrophages, CLEC4F-KCs and some resKCs from Ccr2−/− mice both expressed iNOS but could not control the infection as effectively as WT mice." (PMID 40169598, 2025). "Additionally, we analyzed other specific markers CLEC4F and IBA-1 for KCs and monocytes respectively using immunofluorescent staining, showing that CLEC4F−IBA-1+ monocytes were increased in the livers of μMT mice 6 weeks and 8 weeks after infection than that in WT mice." (PMID 31194740, 2019).
bacterial infection (1 paper, 2013). "We also compared the susceptibility of wild-type and Clec4f−/− mice to L. monocytogenes infection to test whether CLEC4f is involved in bacterial infection." (PMID 23762286, 2013).
CLEC4F also shares sentences with these, for which no sentence is quoted: hepatocellular carcinoma (1 paper); leprosy (1); Thrombocytopenia (1).